MMP2 (matrix metallopeptidase 2)
Diseases named in the same sentence as MMP2 in open-access papers (continued):
Sharing a sentence is not in itself a finding about the gene and the disease.
breast cancer (continued). "Previous studies confirmed that the gene-transfected MMPs breast cancer cell line MDA-MB-436 was inoculated into nude mice and induced the over production of MMP-2 and MMP-9." (PMID 31514467, 2019). "In agreement with our results, it has been reported that nimbolide disturbs migration, invasion, and MMP-2 and MMP-9 expressions in human breast cancer cells and pancreatic cells." (PMID 31391858, 2019). "In agreement with our expression data, functional studies revealed exogenous expression of ERBB2 in ERBB2-negative breast cancer cells (MCF7 and T47D) to enhance the expression of FOXM1 and MMP2." (PMID 31620367, 2019). "In breast cancer cells, TPX2 promotes cancer cell invasion and migration via regulating MMP2 and MMP9 expression." (PMID 31285741, 2019). "We also proved that ERα-36 was also associated with STAT3 and influenced phospholyation and acetylation of STAT3, which was required for IL-6-induced MMP2 and MMP9 expression and breast cancer cell migration." (PMID 31409371, 2019). "In support of this correlation, WISP2 was found to be a negative regulator of migration and invasion via regulation of Snail, E-cadherin, matrix metalloproteinase-2 (MMP-2), and MMP-9 in breast cancer cells." (PMID 30651114, 2019). "Light microscopy showed a higher concentration of cells with positive cytoplasmic staining for MMP-2 and MMP-9 expression in breast cancer than in fibroadenoma." (PMID 31839881, 2019). "Black rice anthocyanins inhibited HER-2+ MDA-MB-453 human breast cancer cell migration and invasion, suppressed the activation of RAF, MEK, and JNK, and downregulated the secretion of MMP-2 and MMP-9." (PMID 31374888, 2019). "MMP3 over-expression in CAFs was observed in mammary glands, MMP2 is over-expressed in gliomas, whereas MMP1 was observed to increase in melanoma and breast cancer." (PMID 30927908, 2019). "Here, we provide new evidences about the clinical relevance of ENO1 and MMPs (MMP-2 and MMP-9) overexpression in breast cancer tissues." (PMID 31416219, 2019). "Biomarkers as matrix metalloproteinases, a family of zinc-dependent endopeptidases, whose major members of the family are MMP-2 and MMP-9 have been related to the pathogenesis of breast cancer." (PMID 31839881, 2019). "The relationships of MMP-2 and MMP-9 to the degradation of the ECM and tumor metastasis are significant; thus, they are regarded as progression markers in breast cancer." (PMID 31783821, 2019). "Light microscopy showed greater concentration of stained cytoplasm for MMP-2 and MMP-9 in breast cancer in comparison to fibroadenoma." (PMID 31839881, 2019). "Our studies demonstrate for the first time that the function of MMP2 and MMP9 in breast cancer cell migration, which is mediated by interactions between ERα-36 and STAT3." (PMID 31409371, 2019). "Experimental evidence suggests that MMP-2 and MMP-9 also contribute to the initiation and progression of breast cancer by cleaving and activating diverse proteins involved in angiogenesis, invasion and metastasis." (PMID 31554180, 2019). "Our previous studies using epithelial breast cancer cells have revealed a complex pattern of expression between MT1-MMP levels and ERK activation into pERK, as well as pro-MMP-2 activation into MMP-2." (PMID 31799217, 2019). "The results indicated that BA significantly decreased the expression of MMP-2 and MMP-9 secreted by breast cancer cells." (PMID 31531187, 2019). "The experiments further demonstrated that SPG-56 inhibited the metastasis of breast cancer in MCF-7 and 4T1-bearing mice by altering the expression of MMP2, MMP9, VEGF, Occludin and Claudin." (PMID 30651572, 2019). "Previous studies have shown that MRE11 overexpression in breast cancer cells leads to cell proliferation by stimulating STAT3 signalling and enhances migration and invasion capabilities through activation of MMP-2 and MMP-9." (PMID 31221177, 2019).
breast cancer (continued). "LPA induces the expression of MMP-2 or MMP-9 in a variety types of cancer cells 32-35, which motivated us to investigate the effect of LPP1 on MMPs in breast cancer cells." (PMID 31534541, 2019). "In human breast cancer MCF7 cells, autocrine/paracrine GH promotes MMP2 and MMP9 metalloprotease release and an EMT phenotype." (PMID 31939481, 2019). "MMP-2 and MMP-9 had been demonstrated to be important prognostic biomarkers in diverse cancers, such as breast cancer, colorectal cancer, and NSCLC." (PMID 31827393, 2019). "Hypermethylated MMP14 and MMP2 promoters have been found in the non-invasive MCF7 breast cancer cell lines, whereas highly migratory glioma cells display hypomethylated promoters coupled to high MMP14 and MMP2 expression levels." (PMID 31466240, 2019). "The current study showed a higher concentration of cells with strong brown cytoplasmic staining for MMP-2 and MMP-9 in breast cancer cells than in fibroadenoma." (PMID 31839881, 2019). "Matrix metalloproteinase-1 (MMP-1), matrix metalloproteinase-2 (MMP-2), cyclooxygenase-2 (COX-2), and epiregulin (EREG) synergistically promote breast carcinoma intravasation by stimulating neoangiogenesis and leaky blood vessel formation." (PMID 31817450, 2019). "The obtained peptide-DOX conjugate can effectively target HER2-positive breast cancers and deliver DOX to nuclei faster due to the release of free DOX in the extracellular matrix through cleavage of MMP-2." (PMID 29405790, 2018). "The purpose of this study was to examine the activity levels of MMP-2 and MMP-9 in a cohort of 80 surgical samples of breast cancer patients, and to uncover their putative correlations with the proteomic assembly of the same patients." (PMID 30060564, 2018). "For example, leukocyte-derived MMP-2 and -9 are able to activate latent TGFβ residing in the ECM by proteolytic cleavage of LTBP1 and subsequently enhance breast cancer growth." (PMID 29874869, 2018). "In the tumor microenvironment, cancer cells coexist with preosteoclasts and release many soluble factors such as IL8, IL11, MMP1, MMP2, TNFα, and PGE2, which determine the direct osteolytic capability of breast cancer cells." (PMID 30126457, 2018). "MMP-2 and MMP-9 activation can particularly enhance tumor cell metastatic potential in breast cancer." (PMID 29423083, 2018). "Another study found a correlation between high expression levels of MMP-2 and MMP-9 and lymph node metastasis and tumor staging in breast cancer patients." (PMID 30518369, 2018). "For example, mRNA levels of MMP-2 and its closely related MMP family member MMP-9 are significantly higher in MDA-MB-231 and MCF-7 breast cancer cell lines (MDA-MB-231 and MCF-7) compared to the normal HS578Bst cell line." (PMID 29874869, 2018). "Further studies reveal that MYOF mainly contributes to metastasis via enhancing the expression of MMP‐2 and regulating EMT in breast cancer cells." (PMID 29164766, 2018). "Overexpression of MMP-2 and MMP-9 is observed in various types of cancer, such as colorectal tumors, melanoma and breast cancer." (PMID 29713337, 2018). "Taken together, we determined that IL-6, CCL2, MMP9, MMP2, and CHOP expression are all inversely correlated with IGF-1R expression in human breast cancer." (PMID 30458886, 2018). "Boxplot representation of MMP2 and CHOP (D, F) expression levels in ER+/PR+ breast cancer compared to TNBC (MMP2: Student’s t test, P < 2.2 × 10− 16; CHOP: P < 2.2 × 10− 16)." (PMID 30458886, 2018). "HGF is believed to act as an initiation signal for the onset of EMT, which results in the upregulation of effector molecules, such as MMP-2 and MMP-9, and activation of STAT-3 to aid EMT and the metastatic dissemination of breast cancer cells." (PMID 30314527, 2018). "Using breast cancer cell lines, McLaughlin and coworkers reported that NEDD9 depletion reduced MMP2 and MMP9, cell invasion and matrix degradation." (PMID 29876004, 2018).
breast cancer (continued). "By gain‐ and loss‐of‐function assays, we show that depletion of Furin in Plac1‐overexpressing breast cancer cells attenuated the Plac1‐induced expression of NICD, HES1, MMP2, and MMP9 and tumor cell invasion and metastasis." (PMID 29704427, 2018). "Flavonoids such as quercetin and EGCG have been shown to decrease the expression of both MMP2 and MMP9 in human melanoma cells and breast cancer, respectively." (PMID 28947953, 2017). "OL (370 μmol/L) reduced breast cancer cell growth and the expression levels of MMP-9 and MMP-2, and induced apoptotic cell death of breast cancer cells." (PMID 28410190, 2017). "Tissue plasminogen activator (tPA) and urokinase plasminogen activator (uPA) are known to activate pro-enzyme forms of MMP-2 and MMP-9 to active forms and tPA and uPA have been proposed as markers for breast cancer progression." (PMID 28880889, 2017). "Evidence indicates that AdSCs release IL-4, IL-8, IL-10, matrix metalloproteinase (MMP)-2, VEGF and SDF-1, which potentiate breast cancer growth and progression." (PMID 28750689, 2017). "Obviously, we found an elevated expression of MMP-2 and MMP-9 in MCF-7, A549 and H1793, while MMP-1 expression was only observed in breast cancer cell line." (PMID 28915603, 2017). "In gastric cancer and breast cancer cells, inhibition of PI3K/AKT signaling pathway repressed MMP2/MMP9 activation and reduced EMT." (PMID 27880942, 2017). "IHC standard reports indicated the expression of PCK26, Vimentin27–29, MMP2 and MMP930, and overexpression of N-Cadherin 131 in SLNs of breast cancer patients with metastasis." (PMID 29259164, 2017). "Further investigation showed that fascin up-regulated NF-κ B activity, uPA, MMP-2 and MMP-9 expression, but down-regulated the expression and nuclear translocation of BRMS1, resulting in a higher ability of breast cancer cells to migrate and invade." (PMID 29285273, 2017). "In our study, we demonstrated that ectopic expression of AKR1B10 promoted breast cancer cell migration and invasion through activation of ERK signaling pathway and up-regulation of expression of MMP2 and vimentin." (PMID 28402270, 2017). "Demethylation of the MMP2 gene promoter increases MMP-2 expression in noninvasive breast cancer cell lines and cells treated with trichostatin A, an HDAC inhibitor, demonstrated increased histone acetylation and reduced MMP2 mRNA expression." (PMID 28116311, 2017). "Work from Kim and colleagues highlighted the role of this cytokine in upregulation of MMP-2 and MMP-9 in the MCF10A breast cancer cell line; it is also known that these MMPs participate in TGFβ cleavage for further cytokine release." (PMID 28633655, 2017). "For example, blocking OPN binding to αvβ3 inhibited OPN-induced tumor growth and angiogenesis, decreased the expression of ILK, uPA, and MMP-2, and prevented OPN-mediated AP-1 activation in breast cancer cells." (PMID 28769537, 2017). "The expression levels of MMP-2 and MMP-9 are reported to be increased in bone metastasis nests of breast cancer." (PMID 29152067, 2017). "This fits with the recent finding that MMP-2 in breast cancer metastasis is predominantly expressed in the tumor stroma, and that MMP-2 plays an important role in breast cancer tumor growth, progression, and metastasis." (PMID 28545495, 2017). "Higher expression of metalloproteinases (MMPs) has been shown in breast cancer cells, and a correlation of reduced TFPI-2 levels with increased expression of MMP-2 mRNA was reported in pancreatic cancers." (PMID 29051606, 2017). "Pretreatment with extract significantly decreased the levels of IL-8, IL-6, MMP-2 and MMP-9 in the breast cancer cells." (PMID 28264501, 2017). "It has been shown that the activation of PIAS1 suppresses the ability of TGFβ to activate matrix metalloproteinase 2 (MMP2) and invasive properties of breast cancer cells." (PMID 26905733, 2016).
breast cancer (continued). "Tang and colleagues confirmed that resveratrol significantly inhibited the migration and invasion of MDA-MB-435 ER-negative human breast cancer cells, insulin-like growth factor (IGF-1)-mediated MMP-2 expression, and PI-3K/Akt signaling pathway activation." (PMID 27999314, 2016). "EGCG and Green tea polyphenols (GTP) mediate epigenetic activation of TIMP-3 levels, resulting in suppression of invasiveness and gelatinolytic activity of MMP-2 and MMP-9 in MDA-MB-231 and MCF-7 breast cancer cells." (PMID 27999314, 2016). "Given that MMP2, COL1A1 and SPARC are all pro-metastatic genes, we suggest these genes play crucial roles in LOX+ breast cancer metastasis." (PMID 27147578, 2016). "Our recent work identified Rab40b GTPase as a protein required for MMP2 and MMP9 secretion from the invadopodia in breast cancer cells." (PMID 27789576, 2016). "In the human breast cancer cell line MCF-7, concentrations of gallic acid as low as 1 μM inhibited MMP-2 expression, however, higher concentrations of 2 μM have been reported for gastric adenocarcinoma cells and 20 μM for osteocarcinoma cells." (PMID 28933410, 2016). "Recently, PTTG1 was shown to regulate MMP-2 via direct promoter regulation, influence Rho-GEF ECT2, and be involved in the invasion and migration of breast cancer cells by promoting EMT." (PMID 26900962, 2016). "MMP2 and MMP9 are secretory proteins, but small amounts of the enzymes have consistently been found on the surface of various cells, including breast cancer cells." (PMID 27042827, 2016). "In breast cancer patients, radiotherapy can increase the plasma level of MMP-9 and the level of MMP-2 was also significantly higher in skin biopsies of women after radiotherapy, relative to non-irradiated skin." (PMID 27282478, 2016). "TSA exhibits anti-invasive properties through upregulation of RECK, which further inhibits MMP-2 and MMP-9 in a variety of cell lines, including breast cancer cell lines and hepatocytes, amongst other cancer types." (PMID 27506904, 2016). "In previous studies, highly expressed FN, MMP-2, and MMP-9 trigger cell invasion and migration in several human carcinoma cells, including breast cancer cells." (PMID 26637807, 2016). "Noteworthy, stratification of all hepatic cancer groups with respect to MMP-2 and MMP-9 activities revealed characteristic patterns specifically in patients with hepatic breast cancer metastases who had undergone SIRT." (PMID 27277077, 2016). "Overall, they identified Rab40b GTPase as the key regulator in MMP-2 and MMP-9 transport and targeting to the plasma membrane in the breast cancer invasion process." (PMID 25629807, 2015). "High expression of MMP-2 (P=1.5e−6), MMP-9 (P=0.027), and MMP-14 (P=0.00051) is predictive of lower RFS in chemotherapy treated for ER− human breast cancer patients." (PMID 28721370, 2015). "Silencing of HMGA2 in the invasive breast cancer cell model MDA-MB-231 affected, in addition to E-cadherin, the expression of invasive genes, such as MMP2 and TNC, and reduced the rate of motility and infiltration of cells through matrigel." (PMID 25492890, 2015). "We analyzed by immunohistochemistry the presence of MMP-2 in tumor cells and IGFBP-2 in the adipocytes around tumor cells in samples of human ductal infiltrant mammary tumors." (PMID 25747684, 2015). "The existing researches suggest that the high expression of gelatinase A and B (MMP2 and MMP9) promote the metastasis of breast cancer." (PMID 26674531, 2015). "Previous studies suggest that cordycepin inhibits MMP-2 and MMP-9 expression and suppresses MAPK/AP-1 and Akt/PI3K pathways in breast cancer and prostate carcinoma cells, suppressing cancer invasiveness." (PMID 25868853, 2015). "In vitro, PMS can inhibit the proliferation, migration and invasion of MDA-MB-231 human breast cancer cell line and 4T1 mouse breast cancer cell line by decreasing MMP9 and MMP2 activity." (PMID 26674531, 2015).
breast cancer (continued). "The elevated phosphorylation and activation of STAT3 is responsible for the enhanced invasive properties and upregulated expression of MMP-2 and -9 in SK-BR-3/EPR breast cancer cells." (PMID 26501276, 2015). "It was found that estradiol and TAM regulate MMP-2, MMP-9 and extracellular endostatin in ER + PR + human breast cancer cells and in vivo." (PMID 26526196, 2015). "miR-33b can decrease the levels of MMP-2, MMP-9, LOX, CXCR4, FN and p-FAK in breast cancer cells by regulating downstream targets." (PMID 25919570, 2015). "MMP-2 and MMP-9 are complex members of the MMP family and demonstrate upregulated expression in breast cancer." (PMID 26599012, 2015). "Consistent with the function of PIAS1 in regulating TGFβ-induced MMP2 activation, we found that expression of wild type PIAS1 suppressed the ability of TGFβ to confer an invasive behavior in MDA-MB-231 breast cancer cells." (PMID 25594015, 2014). "It is of importance to note that MMP-2/-9 plays roles in tumor progression, as over-expression of the MMP-2/-9 gene in transgenic mice led to enhanced tumorigenesis in a breast cancer model." (PMID 25949790, 2014). "It is known that in culture, fibronectin is capable of promoting the expression of MMP-2 in fibrosarcoma cells, cervical cancer cells, MCF7 breast cancer cells and prostate cancer cells." (PMID 25208219, 2014). "In gelatin zymography analyses, we detected the activity of the enzyme MMP2 in lysates and conditioned medium of MDA-MB-231 breast cancer cells." (PMID 25594015, 2014). "Expression of some MMPs correlated with FOXC1 expression, such as MMP7 in breast cancer and MMP1, MMP2, MMP7, and MMP9 in hepatocellular cancer." (PMID 24889262, 2014). "For example, in melanoma and breast carcinoma cells, apoptosis induced by TNF receptor ligands was clearly enhanced by inhibiting MMP-9 (or MMP-2)." (PMID 24956101, 2014). "Inhibiting MMP2 and MMP9 halted the invasion of metastatic breast cancer cells in the embryonic zebrafish." (PMID 24196484, 2013). "Together, our data provide evidence that astrocyte secreted MMP-2 and MMP-9 partially mediate astrocyte secretome induced breast cancer metastasis to brain." (PMID 24324647, 2013). "In breast tumors, gelatinases, MMP-2 and MMP-9 have been shown to play a significant role in growth and metastasis, as their expression is correlated with aggressive forms of breast cancer." (PMID 23536962, 2013). "We performed gelatin zymography to measure the MMP-2 and MMP-9 activities and Western blot to examine the TIMP-1, TIMP-2, MMP-2 and MMP-9 expressions in breast cancer cells." (PMID 23533649, 2013). "The positive signals of Twist, MMP-2 and MMP-9 protein expression were predominantly located in the cytoplasm and/or nucleus of breast cancer cells." (PMID 23935727, 2013). "Northern Blot analysis revealed that the level of MMP-2 and MMP-9 mRNA transcript was higher in breast cancer tissue compared to normal breast tissue." (PMID 23874773, 2013). "Furthermore, we identified that this phenomenon is associated to a MMP-2 decreased activity in the extracellular media and decrease in FAK/Src complex signaling, possibly mediating the anti-invasive effects of azurin in P-cadherin-overexpressing breast cancer cells." (PMID 23894398, 2013). "α-mangostin has been demonstrated to be an inhibitory agent for MMP-2 and MMP-9 in lung and breast cancer." (PMID 23833675, 2013). "Previous studies have suggested that matrix metalloproteinases (MMP-2 and MMP-9) and their inhibitors (TIMP-1 and TIMP-2) play important roles in the invasion and metastasis of breast cancer." (PMID 23935727, 2013). "The specific MMP2/9 Inhibitor II, has been shown to mitigate TGF-β induced invasion of breast cancer cells." (PMID 24196484, 2013). "As shown in breast cancer cells, TGF-β1 strongly induced the expression and activation of MMP-2 and MMP-9; those inductions were dose-dependently inhibited by CX-4945." (PMID 24023938, 2013).